BRAF (B-Raf proto-oncogene, serine/threonine kinase)
Diseases named in the same sentence as BRAF in open-access papers (continued):
Sharing a sentence is not in itself a finding about the gene and the disease.
melanoma (continued). "High-throughput screening based on a gene trap strategies was also developed and validated for malignant melanoma using the A375 cell line harboring a BRAF driver mutation (V600E)." (PMID 31293965, 2019). "BRAF-inhibition decreases the cellular volume of enlarged BRAF-mutated melanoma cells in a glucose dependent manner." (PMID 31671846, 2019). "BRAF mutations have been extensively reported in numerous cancers, including melanomas (50–66%), papillary thyroid tumors (45–50%), CRCs (10%), prostate tumors (10%), and NSCLCs (3%)." (PMID 30975211, 2019). "Approximately 50% of melanomas harbor mutations in BRAF (V-raf murine sarcoma viral oncogene homolog B1), leading to the aberrant activation of the MAPK signaling pathway." (PMID 30866509, 2019). "As the most frequent genetic alteration in melanoma, oncogenic mutations in BRAF gene are observed in 40-50% of patients, contributing to the constitutive activation of the MAPK pathway and oncogenic development." (PMID 31762821, 2019). "Genetic alterations in the MAPK pathway (including the mutation of KRAS, NRAS and BRAF genes) can cooperate in the development of B16 melanomas and CT26 colorectal carcinoma." (PMID 30935124, 2019). "The most common mutation in melanoma BRAF can be detected in the ctDNA of melanoma patients and has been shown to be useful in monitoring patients." (PMID 31671846, 2019). "Long e.t al. compared the sensitivity and specificity of the immunohistochemical staining of BRAF V600E in paraffin-embedded samples of patients with stage 4 malignant melanoma, which required the molecular confir- mation of this mutation for target therapy." (PMID 31531096, 2019). "BRAF mutations of primary melanomas were V600E (26/32, 81,25%) and V600K (5/32, 15,6%) and there was one case showing a rare codon 601 alteration (K601E)." (PMID 31391014, 2019). "Accordingly, in the early stage of an inducible autochthonous model of mouse melanoma, an accumulation of Tregs occurs in the presence of mutated BRAF." (PMID 31762942, 2019). "A general consensus in the field postulates that MEK1 mutations in BRAFV600E melanomas are linked to both intrinsic and acquired resistance to BRAF inhibitors, although these studies were disputed by other evidence." (PMID 30934534, 2019). "The combination of BRAF and MEK inhibitors, such as dabrafenib (D) and trametinib (T), actually represents the standard of care in metastatic or locally advanced BRAF V600 mutated malignant melanomas (MM)." (PMID 30939167, 2019). "Two of these (vemurafenib, Genentech/ Roche; and dabrafenib, Novartis) have shown clinical activity and are approved for treatment of patients with BRAF-mutated melanoma." (PMID 31158244, 2019). "The BRAF inhibitors dabrafenib and vemurafenib induce remarkable clinical responses in patients with BRAF-mutated melanomas." (PMID 30679688, 2019). "Although, the traditional view has been that a driver oncogenic event typically occur as an activating mutation in protooncogene, such as in NRAS and BRAF genes in case of melanoma." (PMID 31217906, 2019). "This binding triggers the sustained activation of the MAPK and the PI3K/AKT pathways, which are frequently upregulated in melanomas through NRAS or BRAF mutation, or PTEN loss, respectively." (PMID 31013837, 2019). "This drug combination has achieved Food and Drug Administration (FDA) approval for the treatment of melanoma displaying the BRAF V600E mutation." (PMID 31882734, 2019). "In other solid tumors such as melanoma and non-small cell lung cancer, BRAF inhibitors were approved for patients with BRAF mutation positive." (PMID 31664962, 2019). "Based on the promising results obtained in melanoma, BRAF-inhibitors have been used also in other BRAF-mutated cancers, with contrasting results." (PMID 31762942, 2019). "Such opportunistic methods employed by BRAF-mutant cells also expose their therapeutic vulnerabilities, as evidenced by the sensitivity of BRAF-mutated melanoma cells to LSD1 and JMJD2 inhibitors." (PMID 31581557, 2019).
melanoma (continued). "Mutations in the Ser/Thr-kinase BRAF (especially the V600E mutation) are responsible for abnormal MAPK pathway signaling in more than 50% of melanoma patients." (PMID 30728057, 2019). "In BRAFV600E-mutated melanoma, the combination of BRAF and MEK inhibitors has led to high response rates (70%) and rapid response induction and symptom control, with a significant prolongation of progression-free survival." (PMID 31028434, 2019). "Blockade of BRAFi-induced autophagy–lysosomal activation in BRAF-mutant melanoma causes increased tumor progression, epithelial-to-mesenchymal-like transition (EMT), and partial resistance to BRAFi therapy." (PMID 30979895, 2019). "Approximately 50% of melanomas carry the activating BRAF(V600E) mutation, which causes constitutive hyperactivation of the MAPK pathway." (PMID 31399133, 2019). "In 82% of RAC1P29S/L cases analyzed there was a co-occurring mutation in one of the three main melanoma driver genes BRAF, NRAS, and NF1." (PMID 31257073, 2019). "BI-78D3 promotes apoptosis in BRAF inhibitor-naive and resistant melanoma cells containing a BRAF V600E mutation." (PMID 31745079, 2019). "For example, SF3B1 hotspot mutations are common in anorectal and vulvovaginal melanomas but are rare in mucosal melanomas from other sites and BRAF mutations are less common in the nasal cavity." (PMID 31320640, 2019). "Five of the 9 patients with melanoma had tumors bearing known mutations (4 with BRAF mutations and 1 with EGFR mutation)." (PMID 31439037, 2019). "In contrast, BRAF5KR exhibited reduced activity to promote cell proliferation in both cell lines, suggesting a crucial role for K27-linked polyubiquitination to maintain BRAF activity in melanoma cells." (PMID 31015455, 2019). "Other successful examples include the treatment of lung cancers harboring mutated epidermal growth factor receptor (EGFR) with EGFR inhibitors, and the treatment of melanomas bearing mutated BRAF with BRAF inhibitors." (PMID 30795816, 2019). "A considerable proportion of melanomas (about 40–50%) and also nevitic lesions present activating mutations in the BRAF oncogene (over 90% V600E)." (PMID 31138295, 2019). "The discovery of this mutation provided the genetic basis for the development of BRAF inhibitors (BRAFi) for the treatment of melanoma." (PMID 31730502, 2019). "After DNA-based detection of the BRAF V600E mutation in melanoma patients, targeted inhibitor treatment is the current recommendation." (PMID 31835364, 2019). "About eight percent of all human tumors (including 50% of melanomas) carry gain-of-function mutations in the BRAF oncogene." (PMID 31581557, 2019). "The efficacy and safety results from an earlier data cut-off of February 29, 2012 (smaller subgroups of patients with NRAS- or BRAF-mutated melanoma) have been previously reported." (PMID 30956763, 2019). "The concordance in BRAF mutations between the index and subsequent melanomas in these studies was low, as in other literature reports." (PMID 31382929, 2019). "Although several treatment regimens to target melanoma harboring the most prevalent BRAF mutation hold great promise with unprecedented response rates, treated patients ultimately develop resistance to therapy after a short period of disease control." (PMID 30642390, 2019). "In all malignancies, V600E is the most commonly observed BRAF codon 600 mutation (at least 89%), followed in melanomas by V600K (9%) and V600R (1–2%)." (PMID 31398831, 2019). "About 50% of human melanomas are strongly associated with BRAF mutations, which renders tumour patients with this type of melanoma usually have high immunosuppression and resistance to vaccine treatment." (PMID 31617076, 2019). "HGF has been described as the main mediator of stroma-induced resistance to BRAF inhibitors in BRAF mutated melanoma, colorectal cancer (CRC) and glioblastoma, by activating MAPK and PI3K/Akt signaling in tumor cells via MET receptor." (PMID 30927908, 2019).
melanoma (continued). "As the potential heterogeneity of BRAF mutations in melanoma has been reported, accurate detection of BRAF mutations are important." (PMID 31817947, 2019). "The BRAF gene mutation is known as one of the most common mutations in melanoma, with V600 as the most common site of mutation." (PMID 31890008, 2019). "It is well-known that the molecular landscape of BRAF V600E-mutated mCRC is more complex and heterogeneous as compared to melanoma." (PMID 31661924, 2019). "BRAF mutations have been found in melanoma, and V600E is the most common mutation in BRAF leading to constitutive activation of the MAPK signaling pathway in malignant melanomas." (PMID 30717768, 2019). "To test this possibility, we examined BRAF essentiality in melanoma, in which BRAF mutations are predictive of sensitivity to BRAF inhibitors, and in colon cancer, in which BRAF mutations are less prevalent and predict only a weak response to BRAF inhibitors." (PMID 30674557, 2019). "The introduction of v-raf murine sarcoma viral oncogene homolog B (BRAF) inhibitors in melanoma patients with BRAF (V600E) mutations has demonstrated significant clinical benefits." (PMID 31416288, 2019). "As approximately 70% of malignant melanoma patients have a hotspot mutation in BRAF or NRAS34, and the mutation being an early event in most cases, single gene analysis is suitable for monitoring these patients during the treatment course." (PMID 31767937, 2019). "It has been demonstrated that BRAF inhibition is associated with enhanced melanoma antigen expression." (PMID 30991686, 2019). "Several studies demonstrate V600E is the most frequently observed BRAF mutation, particularly in melanomas." (PMID 31480291, 2019). "The introduction of genomic biomarkers to guide targeted therapy has also had marked success for patients with BRAF mutation-positive melanoma or HER2-overexpressing gastric or breast cancer." (PMID 31142054, 2019). "An example is BRAF V600 Vemurafenib enrolling patients with different non-melanoma cancers harboring BRAF V600 mutation." (PMID 30813545, 2019). "A total of 30 unique BRAF mutations were detected in 189 BRAF-mutated melanomas, including one tumor with two BRAF mutations." (PMID 31277584, 2019). "For example, binimetinib, the most recent approved MEK1/2 inhibitor for melanoma treatment for combination therapy with a BRAF inhibitor, was able to induce at least a partial response in 20% of melanoma patients with NRAS mutations." (PMID 30987166, 2019). "Acral and mucosal subtypes of melanoma are predominant in the Japanese population, and the overall detection rates of BRAF, NRAS, and KIT mutations are approximately 30%, 12%, and 13%, respectively." (PMID 30675668, 2019). "For instance, in studies considering pathways related to hairy cell leukemia, it was possible to retain relevant information about signaling cascades leading to the activation of the proto-oncogene BRAF associated with melanoma." (PMID 30871264, 2019). "The clarification of the contribution of the atypical NRAS and BRAF mutations to mucosal melanoma pathogenesis will however require the development of suitable cellular and animal models for this melanoma subtype." (PMID 31398831, 2019). "The latest version of the National Comprehensive Cancer Network (NCCN) guidelines recommends BRAF inhibitors in combination with MEK inhibitors as one of the first-line treatments for unresectable melanoma with BRAF mutations." (PMID 31817947, 2019). "Moving from the action of BRAF-inhibitors on immune-infiltrating cells to their effect on cancer cells, it was demonstrated that, in BRAF-mutated melanoma cells, Vemurafenib enhances the presentation of tumor antigens." (PMID 31762942, 2019).
melanoma (continued). "Selumetinib is a potent and highly selective reversible MEK inhibitor (MEK-I), currently approved in combination with vemurafenib, a BRAF-inhibitor (BRAF-I), for advanced BRAF-mutated melanoma patients." (PMID 31196138, 2019). "Based on their somatic mutation profiles, melanomas can be divided into four genomic subtypes: BRAF, RAS (N/H/K), NF1, and triple wild‐type (WT)." (PMID 30312528, 2019). "We examined the impact of CDK11 loss in BRAF-mutant melanoma on more than 700 genes important in cancer signaling pathways." (PMID 30987032, 2019). "Several studies have compared the primary melanoma to the distant metastases with respect to BRAF and NRAS mutation statuses." (PMID 31391014, 2019). "Mutations in BRAF, particularly BRAF p.V600E, are the most commonly detected mutations in melanoma, followed by mutations in NRAS and NF1." (PMID 31684113, 2019). "In the current study, we defined a tumor as immunopositive when >5% of melanoma cells expressed the VE1 staining in accordance with the Cobas BRAF V600E Mutation Test." (PMID 31817947, 2019). "While non-V600E BRAF mutations in melanoma were found to be more common in older patients, these mutations consistently represented between 10 and 20% of BRAF mutations in the 20–29, 30–39, 40–49, and 50–59 age groups." (PMID 30995742, 2019). "Vemurafenib, the first BRAF inhibitor (BRAFi) approved for BRAF‐mutated melanoma, induces a clinical response in a large proportion of patients with an overall response rate (RR) of up to 69%." (PMID 31115969, 2019). "This differs from melanoma, in which around 20% of BRAF V600 mutations are non-V600E (mostly V600K, but also V600R or others)." (PMID 30995742, 2019). "It was shown that ectopic expression of EGFR in melanoma cells was sufficient to cause vemurafenib (BRAF inhibitor) resistance." (PMID 31649529, 2019). "Recently, the FDA approved the other two drugs named dabrafenib and ipilimumab as therapy for patients with BRAF V600E mutation-positive in melanoma." (PMID 30925905, 2019). "In our real‐world retrospective analysis, patients with advanced BRAF V600 mutated melanoma treated with front‐line niv/ipi or aPD‐1 had an increased likelihood of survival compared to those treated with front‐line BRAF/MEKi." (PMID 31677253, 2019). "Early studies in mice showed that PLX4720 downregulated the expression of the CCL2 gene and of its protein, both in BRAF (V600E)-mutated melanoma xeno-graphs and in de novo occurring melanomas." (PMID 31762942, 2019). "Despite marked success in BRAF-mutated melanoma and pre-clinical trials in BRAF mutant colorectal cell lines, BRAF inhibition has not shown clinical benefit in BRAF-mutated mCRC." (PMID 30646508, 2019). "A great breakthrough was the approval of vemurafenib in 2002, which was the first BRAF inhibitor developed against BRAF-mutated melanoma." (PMID 31652660, 2019). "More specifically, 50% of all melanomas harbour BRAF (v-Raf murine sarcoma viral oncogene homolog B) V600 mutations, 15–30% NRAS (neuroblastoma RAS viral oncogene homolog) mutations, whereas NF-1 gene is altered in 12–18% of cases." (PMID 31672982, 2019). "A significant correlation between elevated levels of C-X-C chemokine receptor 4 (CXCR4) mRNA and a BRAF mutation was found in tissue samples from patients with melanoma." (PMID 31762942, 2019). "For example, mutations in the serine-threonine protein kinase BRAF are present in up to 15% of all cancers, with an increased incidence of up to 70% in melanoma." (PMID 31672130, 2019). "Challenges in this area include the considerable heterogeneity among melanoma subtypes, for example the molecular differences between UV associated cutaneous melanomas, non-V600E BRAF mutant melanomas, and acral and mucosal melanomas." (PMID 31861163, 2019). "Approximately 50% of melanomas at diagnosis harbour mutations in the B-Raf proto-oncogene serine/threonine kinase (BRAF) gene, a key serine-threonine kinase in the MAPK signalling pathway." (PMID 31557826, 2019).
melanoma (continued). "This drug has shown in vitro and in vivo efficacy in combination with targeted therapies like EGFR inhibitors in EGFR mutation-positive NSCLC or BRAF/MEK inhibitors in BRAF mutation-positive melanomas." (PMID 31150457, 2019). "It was also shown that Zeb2 is involved in acquired resistance to the BRAF inhibitor in BRAF-mutated melanoma." (PMID 31231466, 2019). "BRAF mutations occur in 40–50% of melanomas and treatments with specific inhibitors (e.g., vemurafenib, dabraenib) were reported to be effective in a metastatic disease." (PMID 31481958, 2019). "We show that lncRNA IGF2AS, MEG3, and Zeb2NAT are independent prognostic factors in BRAF-mutated advanced melanoma patients treated with vemurafenib." (PMID 31231466, 2019). "The presence of NRAS and BRAF mutations in mucosal melanomas raises the question of their therapeutic potential for this particularly deadly form of melanoma, which has not yet fully benefited from genomics-era advances in precision oncology." (PMID 31398831, 2019). "PLX4720 (Vemurafenib) showed more encouraging results as reported in a Phase II clinical trial, where a favorable response was observed in 48% of BRAF mutated melanoma patients." (PMID 31762942, 2019). "BRAF somatic missense mutations occur in 66% of melanomas, and the most frequent mutation (B-RafV600E) is found in approximately 50% of melanomas, rendering B-Raf inhibitor development an important anticancer strategy." (PMID 31198408, 2019). "There were no other variables included in the data set that were able to explain this difference, although one missing feature is cancer subtype (i.e., BRAF-mutant melanoma) which has a much higher risk of recurrence." (PMID 32083018, 2019). "For example, while BRAF inhibitors have shown to be effective in melanomas carrying BRAF mutations, they have demonstrated little effect in the treatment of BRAF mutant colon cancers." (PMID 30636931, 2019). "Recently, detection of the BRAF V600E mutation by immunohistochemistry (IHC) using the anti-BRAF V600E monoclonal VE1 antibody was found to be possible in melanoma, thyroid carcinoma, and colorectal cancer." (PMID 31234388, 2019). "Accelerated glucose metabolism is a well-known feature of melanomas as the BRAF oncogene causes the upregulation of genes involved in glycolysis." (PMID 31334125, 2019). "First line B-Raf inhibitors are capable of managing the majority of melanoma patients that express the BRAF V600E mutation." (PMID 30909892, 2019). "The development of immunotherapy strategies focused on the tumor microenvironment of BRAF-mutated tumors will hopefully provide new tools for a personalized treatment of patients with melanoma or refractory thyroid cancer." (PMID 31762942, 2019). "When compared to the previous studies for all melanoma subtypes in Asia, the prevalence of BRAF V600 mutation in this study was still lower than other Asian countries." (PMID 31890008, 2019). "Significant association with old age and primary tumors of head/neck/upper back suggest chronic solar damage as a contributing factor for melanomas harboring BRAF p.V600K or class-3 mutations." (PMID 31277584, 2019). "Genetic silencing and pharmacological inhibition of the ERK5 pathway reduce growth of melanoma cells and xenografts harboring wild-type (wt) or mutated BRAF (V600E)." (PMID 30901834, 2019). "Melanomas with wild-type BRAF likely have mutations in the upstream proteins of the MAPK pathway, such as NRAS or KIT." (PMID 31890008, 2019). "The glutamate for valine substitution at codon 600 in exon 15 (V600E) is the most common BRAF mutation, and is found in more than 90% of human malignancies such as papillary thyroid cancer, ovarian cancer, melanoma and CRC." (PMID 30658510, 2019). "Mutationally activated BRAF is expressed in several cancers, including melanoma, and the most common BRAF mutation leads to the substitution of a glutamic acid for valine at amino acid 600 (V600E) in the kinase domain of the protein." (PMID 31514399, 2019).